IL4 (interleukin 4)
Diseases named in the same sentence as IL4 in open-access papers (continued):
Sharing a sentence is not in itself a finding about the gene and the disease.
trachoma (2 papers, 2008 to 2024). "Additional cytokines (Th1, IL-12p40 [r = −0.212, P<0.01], and Th2, IL-4 and IL-13 [r = −0.165 and −0.189, respectively, P<0.05 for both]) were negatively associated with chronic scarring trachoma, suggesting a protective role." (PMID 18628987, 2008). "Studies conducted on human cohorts at different stages of trachoma revealed an association between chronic trachoma and the local presence (in mucosal sponges) of IL-1RA (an antagonist of the pro-inflammatory IL-1), as well as IL-4 and IL-13 (associated with Th2 response)." (PMID 39093884, 2024). "No mRNA expression was detected for the Th2 cytokines IL-4 and IL-5 for any trachoma grade." (PMID 18628987, 2008).
transitional cell carcinoma of the bladder (2 papers, 2013 to 2022). "Other enriched genes we found (AR, GNB3, HHLA2 and IL4) were related to transitional cell carcinoma of the bladder (also known as Urothelial carcinoma)." (PMID 35565241, 2022).
tuberculous pleurisy (2 papers, 2012 to 2021). "Therefore, the PFMCs from tuberculous pleurisy patients have the ability to produce IL-4 and IL-15 when stimulated with M.tb." (PMID 23028695, 2012). "In patients with tuberculous pleuritis, the increase in IFN-γ mRNA and the decrease in IL-4 mRNA were even more significant in the pleural fluid cells, compared with those from PBMCs." (PMID 34202662, 2021).
type IV hypersensitivity reaction (2 papers, 2025). "A type IV hypersensitivity reaction, Th2-mediated and driven by interleukin-4 (IL-4), IL-5 and IL-13, promoting IgE production by B cells and activating eosinophils and mast cells, has been suggested." (PMID 40371306, 2025).
Ureteral obstruction (2 papers, 2016 to 2024). Obstruction of the flow of urine through the ureter. "Three days after ureteral obstruction, we intravenously transferred M0, M (IFNγ + LPS) or M (IL4 + IL13) and assessed the degree of inflammation and fibrosis 4 days later, as displayed in the experimental design." (PMID 27621813, 2016). "NLRP-3 can also promote an M2 phenotype by increasing IL-4 expression and activating the IL-4/STAT6 pathway in a unilateral ureteral obstruction mice model." (PMID 39457523, 2024).
viral pneumonia (2 papers, 2020). Inflammation of the lung parenchyma that is caused by a viral infection. "Decrease the level of serum IL-4 and expression of H1N1 mRNA and Aquaporin 1 (AQP1) protein in mice model with viral pneumonia." (PMID 33192523, 2020).
abscess (1 paper, 2009). An inflammatory process characterized by the accumulation of pus within a newly formed tissue cavity which is the result of a bacterial, fungal, or parasitic infection or the presence of a foreign body. "Also, abscess tissue of infected mice treated with NO-np exhibited reduced levels of IL-4 and IL-10." (PMID 19915659, 2009).
Acanthamoeba infection (1 paper, 2025). "Several cytokines, such as interferon-gamma (IFN-γ), interleukin (IL)-4, IL-10, IL-17A, IL-17F, and IL-22, are rapidly produced and secreted in response to Acanthamoeba infection." (PMID 40109888, 2025). "Several cytokines, for example, IFN-γ, IL-4, IL-10, IL-17A, IL-17F, and IL-22, were reported to rapidly produce and secrete in response to the Acanthamoeba infection but not IL-1β cytokine." (PMID 40109888, 2025).
acral melanoma (1 paper, 2022). "In addition, we compared plasma cytokine levels according to anatomic sites, and patients with acral melanoma showed lower levels of IL-4 than patients with non-acral melanoma." (PMID 36405903, 2022). "It suggests that immunotherapy using IL-4 or immune-checkpoint inhibitors may have lower therapeutic effects on the acral melanoma than non-acral melanoma, however, further research is needed on this issue." (PMID 36405903, 2022).
Acute bronchitis (1 paper, 2021). Inflammation of the large airways of the lung with rapid onset and short course usually associated with cough, mucus production, shortness of breath, wheezing, and chest tightness. "The molecular genetic testing of the IL4 gene of a single nucleotide polymorphism C-33T was performed in 35 children with recurrent episodes of acute obstructive bronchitis and 35 children with acute bronchitis." (PMID 35027973, 2021). "The next stage of work performed a molecular genetic study of polymorphic loci C-33T gene IL-4 in children with recurrent episodes of acute obstructive bronchitis compared with the data of children with acute bronchitis." (PMID 35027973, 2021).
acute laryngitis (1 paper, 2024). An acute inflammatory process affecting the larynx. "Multivariate logistic regression analysis indicated that TNF-α, IL-4, IL-6, IL-17, and IFN-γ were risk factors for the efficacy of treatment in children with acute laryngitis and laryngeal obstruction after adjustment for confounders, such as age and gender." (PMID 39969319, 2024).
acute leukemia (1 paper, 2018). A clonal (malignant) hematopoietic disorder with an acute onset, affecting the bone marrow and the peripheral blood. "The −1098T/−589C/−33C polymorphism in IL-4 gene was associated with increased susceptibility to CDC in acute leukemia patients whereas the −1098T/−589T/−33T polymorphism was associated with decreased susceptibility." (PMID 29371502, 2018). "An association between genetic variants in IL-4 gene and susceptibility to chronic disseminated candidiasis (CDC) was found in a cohort of 90 patients with acute leukemia, of which 40 suffered from CDC." (PMID 29371502, 2018).
adenocarcinomas of gastric cardia (1 paper, 2020). "Patients with adenocarcinomas of gastric cardia (CC) and GC patients had significantly higher IL-4 concentration than ESCC patients and GC patients—significantly higher as compared to CRC patients as well." (PMID 32512917, 2020).
alcohol addiction (1 paper, 2020). "The data presented here extend the previously reported association of ADCY9, PECAM1, and IL4 with nicotine or alcohol addiction and psychiatric disorders." (PMID 33328875, 2020).
alexithymia (1 paper, 2021). An agnosia that is a deficiency in understanding, processing, or describing emotions. "In a preliminary study, we observed a significant positive correlation between serum levels of IL-4 and alexithymia; however we found the opposite result when we studied in vitro production of IL-4 by phytohaemagglutinin stimulated peripheral blood lymphocytes." (PMID 34987425, 2021). "Lymphocyte subset counts (CD4, CD8), in vitro production of interleukin 1β (IL-1β), IL-2, IL-4, and IL-10 by phytohemagglutinin stimulated peripheral blood lymphocytes, as well as serum cortisol levels, were compared between women with and without alexithymia." (PMID 34987425, 2021).
Alport syndrome (1 paper, 2025). A rare renal disease characterized by glomerular nephropathy with hematuria progressing to end-stage renal disease (ESRD), frequently associated with sensorineural deafness, and occasionally with ocular anomalies. "The role of inflammatory markers cyclooxygenase-2, Prostaglandin E2, Interleukin 4, and Plasminogen activating inhibitor 1 in Alport syndrome that are causally connected and have a role in the development and course of Alport disease was delineated." (PMID 39856623, 2025). "In this study, we delineated the role of inflammatory markers cyclooxygenase-2, Prostaglandin E2, Interleukin 4, and Plasminogen activating inhibitor 1 in Alport syndrome that are causally connected and has a role in the development and course of Alport disease." (PMID 39856623, 2025). "IL-4 has a role in the modulation of the pro-inflammatory response and the development of renal tubule-interstitial injury in Alport syndrome." (PMID 39856623, 2025). "The study aimed to elucidate the role of cyclooxygenase-2, Interleukin 4, Plasminogen activating inhibitor 1, and Prostaglandin E2 in the development and course of Alport syndrome." (PMID 39856623, 2025). "In this study, we aimed to elucidate the role of cyclooxygenase-2, Interleukin 4, Plasminogen activating inhibitor 1, and Prostaglandin E2 in the development and course of Alport syndrome." (PMID 39856623, 2025). "According to some researchers, IL-4 may provide a therapeutic option for Alport syndrome by reducing inflammation and delaying the course of the illness." (PMID 39856623, 2025). "In Alport syndrome, immunological modulation with interleukin-4, costimulatory blocking of T-cell activation, or suppression of macrophage migration may play a role in Alport syndrome treatment." (PMID 39856623, 2025).
anal carcinoma (1 paper, 2023). "Conversely, there were a number of productive immune genes contributing to ‘defense response’ in non-recurrent anal cancer isolates such as IL4, HLA-A, CD200R1, and CD96." (PMID 37177979, 2023).
anal prolapse (1 paper, 2022). "Reduces anal prolapse, surrounding hyperemia by decreasing MPO activity, serum IL-1β, IL-6, TNF-α levels, and increasing IL-4, IL-10 levels." (PMID 35548468, 2022).
anaplastic thyroid cancer (1 paper, 2024). "By analyzing 85 samples from the GSE33630 dataset, we found that POSTN and IL-4 were significantly up-regulated both in papillary thyroid cancer and anaplastic thyroid cancer tissues relative to normal thyroid tissues and POSTN levels were positively correlated with IL-4 in papillary thyroid cancer." (PMID 38773979, 2024).
anisakiasis (1 paper, 2019). Infection with roundworms of the genus anisakis. "IL-4 secretion triggers IgE production by B-lymphocyte, while IL-5 involved in eosinophilic production under anisakiasis." (PMID 31849412, 2019).
anogenital warts (1 paper, 2021). "We investigated the role of interleukin-4 (IL-4) and interferon-gamma (IFN-γ) as ex vivo immunologic predictors to estimate the response to the bivalent HPV vaccine as a potential immunotherapy for cutaneous and anogenital warts." (PMID 34835211, 2021).
Anorexia (1 paper, 2017). Lack of desire to eat (loss of appetite). "Cachexia often appears with anorexia as a result of imbalances between pro-inflammatory (e.g., TNF-α, IL-1, IL-6, interferon-gamma [IFN-γ]) and anti-inflammatory cytokines (e.g., interleukin-4 [IL-4], interleukin-12 [IL-12], interleukin-15 [IL-15])." (PMID 28177923, 2017).
anorexia nervosa (1 paper, 2019). A disorder most often seen in adolescent females characterized by a refusal to maintain a minimally normal body weight, an intense fear of gaining weight, a disturbance in body image, and, in postmenarcheal females, the development of amenorrhea. "Although the Th2 pathway seems to be favored in anorexia nervosa and primary malnutrition, with increased IL-4 as well as decreased IL-2 production, pro-inflammatory cytokines appear to be upregulated in anorexia nervosa." (PMID 31717370, 2019).
aortic coarctation (1 paper, 2016). "IL-4 was also reported to be upregulated in cardiac fibrosis following aortic coarctation in mice, an observation that was attenuated with IL-4 neutralizing antibody suggesting that the cytokine plays a role in the development of cardiac fibrosis." (PMID 26771187, 2016).
arterial disorder (1 paper, 2016). An impairment of the structure or function of the blood vessels which carry blood away from the heart. "We further validated the in vitro results in human arterial lesions and mouse models of arterial disorders, neither of which is solely regulated by IFNγ or IL-4, to provide clinically translatable evidence." (PMID 27796300, 2016).
asthenia (1 paper, 2020). Clinical sign or symptom manifested as debility, or lack or loss of strength and energy. "THD has synergistic and additive antiemetic, anti-asthenia, and analgesic effects of corticosteroids 57, 58; it inhibits the expression of cytokines without affecting levels of IL-2, IL-4, and IL-10 59, 60, thus offering the possibility of steroid-sparing or steroid-replacement therapy." (PMID 32489473, 2020).
atopic march (1 paper, 2023). sequential manifestations of different allergic diseases such as eczema, asthma and rhinitis. "In particular, the T helpers 2 (Th2) subset, through its cytokine signatures made of interleukins (ILs), such as IL-4, IL-5, IL-10, and IL-13, as well as mast cells and their related histamine pathways, contribute greatly to the perpetuation and evolution of the atopic march." (PMID 36675006, 2023).
Atrophy (1 paper, 2025). Any weakening or degeneration, especially through lack of use. "Our results confirmed the key role of AQP4 expression for the presence of brain lesions and atrophy, but were also able to identify the relevant biological pathways, including the activation of the complement cascade, the regulation of IGF and uptake by IGFBPs, and IL-4, -13, and -10 signaling." (PMID 39891565, 2025).
attention deficit-hyperactivity disorder (1 paper, 2020). A disorder characterized by a marked pattern of inattention and/or hyperactivity-impulsivity that is inconsistent with developmental level and clearly interferes with functioning in at least two settings (e.g. at home and at school). "Nevertheless, both autism spectrum disorders (ASD) and attention deficit hyperactivity disorder (ADHD) are associated with increases in adaptive immune (T) cell cytokines, specifically Th2-like cytokines (IL-4, IL-6, and/or IL-10), or decreases in Th2-like cytokines (IL-2 and/or IFNγ)." (PMID 33424735, 2020).
autonomic dysfunction (1 paper, 2025). "Immunofluorescence staining revealed that autonomic dysfunction in AR mice was ameliorated by IL-4 NAb, as evidenced by the up-regulation of TH and NPY and down-regulation of ChAT and VIP in the nose." (PMID 41019284, 2025).
Autosomal dominant hyper-IgE syndrome (1 paper, 2018). 2000 IU/ml), recurring staphylococcal skin abscesses, and recurrent pneumonia with formation of pneumatoceles. "In other experiments, PBMCs isolated from healthy donors or from autosomal dominant hyper-IgE syndrome (STAT3 loss-of-function) subjects were cultured with combinations of IL-4 and IL-10." (PMID 31026808, 2018). "PBMCs from autosomal dominant hyper-IgE syndrome individuals failed to consistently modulate IgE production in response to IL-4 and IL-10." (PMID 31026808, 2018).
avian influenza (1 paper, 2022). Infection of domestic and wild fowl and other birds with influenza A virus. "In contrast, H5N6 VLPs not only elicited higher neutralizing antibody titers, ranging from 640 to 1280, but also induced higher IL-2, IL-4, IL-5, IFN-γ and TNF production, thus indicating that H5N6 VLPs may be a potential vaccine candidate for broad-spectrum H5Nx avian influenza vaccines." (PMID 35632667, 2022).
bacterial vaginosis (1 paper, 2025). Infection caused by bacterial overgrowth in the vagina. "Exact causes of RVVC are unclear, but factors such as microbiology, altered immune responses, genetic polymorphisms, bacterial vaginosis, mannose-binding lectin (MBL) and interleukin-4 (IL-4) deficiencies, antibiotics, sexual activity, and diet contribute to it." (PMID 40091959, 2025).
basal cell carcinoma (1 paper, 2021). A carcinoma involving the basal cells. "CD4+CD25+Foxp3+ T-cells can be found intermingled with human basal cell carcinoma along with the TH2 cytokines IL-4 and IL-10." (PMID 34771569, 2021).
beryllium-disease (1 paper, 2016). "Notably, this single mutation seems to drive helper CD4 T cells in susceptible individuals to secrete Th1-type cytokines, such as gamma-interferon, but not IL-4, leading to beryllium-induced hypersensitivity and chronic beryllium-disease." (PMID 27959918, 2016).
biliary atresia (1 paper, 2021). A rare, biliary tract disease characterized by progressive obliterative cholangiopathy of the intra- and extrahepatic bile ducts, occurring in the embryonic/ perinatal period, leading to severe and persistent neonatal jaundice and acholic stool. "It is consistent with higher IL-2, IL-4, IL-6, IL-10, TNFα, and IFN-γ in patients with biliary atresia." (PMID 34630385, 2021).
blepharoconjunctivitis (1 paper, 2020). Inflammation of both the eyelids and the conjunctiva. "Although the underlying mechanism of blepharoconjunctivitis in AD patients is still not completely elucidated, some authors have suggested that the blockade of IL-4 and IL-13 may increase the activity of specific ligands, such as OX40 ligand, involved in atopic keratoconjunctivitis." (PMID 32183179, 2020).
bone metastasis (1 paper, 2024). Transfer of a neoplasm from its primary site to bones. "Patients with bone metastasis had higher serum IL-22 levels (p = 0.008), and patients with brain metastasis had lower IL-4 levels (p = 0.025)." (PMID 39502692, 2024).
bowel cancer (1 paper, 2013). "A previous study has shown that at the completion of chemotherapy treatment for bowel cancer involving Folfox chemotherapy (combination of 5-Fluroruracil, Folic acid and Oxaliplatin), levels of IL-4 and IL-10 were reduced in plasma." (PMID 23951199, 2013).
bronchial NET (1 paper, 2020). "On the contrary, the levels of IL-4 decreased already at 10 days, as compared to baseline untreated control in sera from the patients affected by bronchial NETs." (PMID 32766136, 2020). "Moreover, we have evaluated the effects of lanreotide on Th1 and Th2 functional profile on NET cell lines (typical bronchial NET NCI-H727 and pancreatic NET BON-1) and in patients with advanced NETs by evaluating specific cytokine patterns (IL-2, IL-4, IL-6, IL-10, IFN-γ, and TNFα)." (PMID 32766136, 2020).
C. perfringens infection (1 paper, 2025). "Compared to the CON group, C. perfringens infection significantly elevated serum levels of IL-1β, IL-6, and TNF-α, while suppressing IL-4 and IL-10 (p < 0.05)." (PMID 40427288, 2025). "In line with earlier findings in piglets and IPEC-J2 cells, we observed that C. perfringens infection significantly increased the serum levels of IL-1β, IL-6, and TNF-α, while decreasing those of IL-4 and IL-10." (PMID 40427288, 2025).
Candidemia (1 paper, 2021). A form of invasive candidiasis where species of CANDIDA are present in the blood. "Serum levels of IL-4 were significantly higher in the candidemia group than in healthy controls only." (PMID 34684298, 2021).
cellulitis (1 paper, 2022). Inflammation of the dermis and subcutaneous tissues caused by a bacterial infection. "However, long-term treatment with immunosuppressive agents such as fingolimod and IL-4/IL-13-neutralizing antibodies may be a risk factor for infection (e.g., cellulitis)." (PMID 35886961, 2022).
cervical adenocarcinoma (1 paper, 2021). An adenocarcinoma arising from the cervical epithelium. "IL4 and IL13 can upregulate CD44 expression in human cervical adenocarcinoma cell lines and colonic epithelial cell lines." (PMID 35187044, 2021).
Chagas cardiomyopathy (1 paper, 2025). A disease of the cardiac muscle developed subsequent to the initial protozoan infection by trypanosoma cruzi. "Research suggests that individuals at high risk of sudden death in Chagas cardiomyopathy exhibit elevated serum levels of IFN-γ, TNF-α, IL-6, IL-2, IL-10, and IL-4 compared to those at low risk." (PMID 39907396, 2025).
Chédiak–Higashi syndrome (1 paper, 2019). "Additionally, gingival atypical fibroblasts in cases of Chédiak–Higashi syndrome significantly intensify the expression of IL-4 and IL-10 along with other cytokines." (PMID 31443525, 2019).
Cholecystitis (1 paper, 2021). The presence of inflammatory changes in the gallbladder. "IL-4, an interleukin mostly secreted by immune cells, also basophils, neutrophils and activated Th2, serves a diverse purpose in cholecystitis—it is responsible for T cell differentiation in Th2, proliferation of various tissues, including smooth muscle cells, endothelium and neurons." (PMID 34449702, 2021).
cholelithiasis (1 paper, 2021). The presence of crystallized deposits forming in the gallbladder or biliary tree, primarily composed of cholesterol, bilirubin, and bile. "A study made by Issa and Muthena showed that IL-4 indeed is in a decreased concentration in patients with cholelithiasis." (PMID 34449702, 2021).